EPCAM (epithelial cell adhesion molecule)
Diseases named in the same sentence as EPCAM in open-access papers (continued):
Sharing a sentence is not in itself a finding about the gene and the disease.
tumor (continued). "The primary tumor cells showed inhibition of EpCAM expression by -0.5 fold and -2.4 fold in siRNA and chimeric construct treated cells respectively." (PMID 26176230, 2015). "The structure is typical of a carcinoma, with well-delineated and compact tumor islets positive for EpCAM, surrounded by a stroma enriched in collagen." (PMID 26528284, 2015). "Mechanistically, the tumor-promoting effect of G9a appears to bypass its known downstream signaling molecules such as EpCAM, PPARγ, and Wnt." (PMID 25595900, 2015). "Conventional strategy of anti-EpCAM capture and immunostaining of cytokeratins (CKs) to detect circulating tumor cells (CTCs) is limited by highly heterogeneous and dynamic expression or absence of EpCAM and/or CKs in CTCs." (PMID 26267323, 2015). "Approximately 20% of circulating cells in preoperative patients were CD117+EpCAM+ suggesting a subset of tumor-derived circulating CD117+ cells." (PMID 25595903, 2015). "Metastatic PC3 tumor cells were detected in the lung, peritoneal cavity, and bone of untreated mice and in mice treated with control PBLs, whereas treatment with EpCAM-specific PBLs significantly inhibited PC3 metastasis and prolonged mouse survival." (PMID 25636521, 2015). "The tumor cells were incubated with PBLs transduced with either the EpCAM specific CAR or control retroviruses." (PMID 25636521, 2015). "Epithelial cell adhesion molecule (EpCAM) is a well-known cancer stem cell (CSC) marker expressed on cell surface and regarded as a tumor associated antigen." (PMID 26176230, 2015). "Our findings provide direct evidence that our anti-EpCAM antibody is able to inhibit tumor cell proliferation." (PMID 26317650, 2015). "To enrich for tumor cells we utilized the antigen EpCAM, which has also been observed to be upregulated on CSCs and appeared itself to be an indicator of stem-like features." (PMID 25999351, 2015). "We consider that sEpCAM levels in different tumor entities and individual patients should be evaluated prior to applying anti-EpCAM antibody-based cancer therapies, since sEpCAM neutralizes catumaxomab activity, making therapy less efficient." (PMID 25947366, 2015). "Anti-EpCAM-dependent antibody capture and tumor cell size-based filtration currently constitute common strategies for isolating CTCs." (PMID 26267323, 2015). "These contrasting results have been attributed to a defective expression of EpCAM on tumor cells leading to their escape from immunomagnetic trapping." (PMID 26571236, 2015). "Icaritin decreased the proportion of EpCAM-positive (a HCICs marker) cells, suppressed tumorsphere formation in vitro and tumor formation in vivo." (PMID 26376676, 2015). "The essential requirement for EpCAM in these processes highlights the potential for using EpCAM as a target for blocking tumor invasion in the local environment." (PMID 26356670, 2015). "For example, the adjacent normal cells from patient-3 contained CD49f-/EpCAM+ mature cells, whereas the tumor cells were mainly luminal progenitors." (PMID 26311223, 2015). "The PEI nanocomplex fabricated with EpApt and siEp was able to target EpCAM tumor cells, deliver the siRNA and silence the target gene." (PMID 25576037, 2015). "For the enrichment beads coated with antibodies against specific antigens present on the cell surface, especially towards the human EpCAM or antibody against tumor specific markers can be used." (PMID 26167450, 2015). "Tumor tissue sections were prepared, and immunohistochemistry was performed with EpCAM, Ki67, and VEGFA antibodies." (PMID 26356670, 2015). "The spiral biochip uses inherent centrifugal forces for continuous, size-based, and EpCAM-independent separation of tumor cells." (PMID 25398926, 2015). "Glycosylation of EpCAM demonstrates some degree of tissue specificity and was enhanced in tumor vs. normal tissue." (PMID 25477371, 2015).
tumor (continued). "The loss of sphere-forming capacity and efficacy of tumour formation for CD24- MM cells can be linked to their loss of several other stemness markers, including CD47, EpCAM and OCT4, as shown for the tumour tissue." (PMID 25932953, 2015). "E-cadherin is an epithelial cell adhesion molecule, and its loss has been reported to be a prerequisite for the onset of EMT and tumor cell migration." (PMID 26123483, 2015). "This is by far lower than EpCAM gene expression rates described for tumor cells of malignant effusions and for cell surface protein studies using microfluidic chips." (PMID 25947366, 2015). "BiTE® molecules act through linking tumor cells expressing EpCAM to CD3 T cell receptors with single-chain bispecific antibody constructs." (PMID 26474755, 2015). "Obtained tumor cells, free of anti-EpCAM perturbing and hypotonic damage, are eligible for primary tumor cell culture as well as a series of downstream analyses." (PMID 26718583, 2015). "In our experiments, we targeted CHO transfectants and tumor cells with high to moderate EpCAM expression." (PMID 26510188, 2015). "Between 3–50 of the indicated tumor cells labeled with MitoTracker were spiked into 7.5 ml of human blood, and subsequently subjected to non-EpCAM-dependent SE or antibody capture methodology." (PMID 26267323, 2015). "Based on these results, it can be concluded that EpCAM is suitable for use as an EC biomarker, therapeutic target, and effective parameter for tumor transfer and prognosis evaluation by aptamer SYL3C staining." (PMID 26687301, 2015). "Epithelial cell adhesion molecule (EpCAM) is a transmembrane glycoprotein, which is frequently and highly expressed on carcinomas, tumor-initiating cells, selected tissue progenitors, and embryonic and adult stem cells." (PMID 25477371, 2015). "EpCAM is highly expressed on membrane of epithelial tumor cells and has been detected as soluble/secreted (sEpCAM) in serum of cancer patients." (PMID 25947366, 2015). "The tumor sizes of control MDA-MB-231 cells were 8389 ± 968 mm3, which were significantly larger than the tumor sizes of xenografts derived from si-EpCAM-transfected MDA-MB-231 cells (3240 ± 846 mm3, P < 0.01)." (PMID 26356670, 2015). "Solitomab acts by engaging resting polyclonal CD8+ and CD4+ T cells for highly potent redirected lysis of target tumor cells that express EpCAM." (PMID 26474755, 2015). "In this preliminary effort, we use a commercially available and chemically modified tube to selectively capture circulating tumor cells (CTCs) from the blood stream by immobilizing human anti-EpCAM antibodies on the tube's interior surface." (PMID 26176235, 2015). "To further explore the effect of EpCAM on tumor growth and metastasis in vivo, we injected si-EpCMA-transfected MDA-MB-231 cells into nude mice." (PMID 26356670, 2015). "Since EMT tumor cells have been reported to only weakly express epithelial surface antigens, including EpCAM, EMT tumor cells are less likely to be detected by the Cell Search® System." (PMID 24765158, 2014). "The principle of CellSearch system to detect CTC is based on the expression of epithelial cell adhesion molecule (EpCAM) on the tumor cell surface and cytokeratins (CKs) in the same tumor cell." (PMID 25026283, 2014). "Many Vγ9Vδ2 T cells attached to each EpCAM+ tumor cell in the ascites 24 h after their i.p. injection." (PMID 24515916, 2014). "Specific drugs (catumaxomab and edrecolomab) targeting EpCAM have been developed, which can significantly reduce the size of tumor used alone or in combination with standard treatment, demonstrating the potential of such targeting strategies." (PMID 24765173, 2014). "The EpCAM promoter contains a CpG island, the methylation of which inversely correlates with EpCAM expression, tumor invasion and progression in various cancer types." (PMID 24489952, 2014).
tumor (continued). "The rare double-positive CD133+EpCAM+ cell subset was also present in six of the seven tumor samples at a 2.7 times higher proportion than in the healthy lung tissue [median values 0.1 (0.01–0.39 %) and 0.037 (0.01–0.0443 %), respectively; p = 0.16]." (PMID 23959111, 2014). "Suppression of EPCAM attenuates tumor progression and downregulates transcription factors that are involved in EMT reprogramming." (PMID 24944582, 2014). "Analysis of a peripheral blood sample and ascites sample with the CellSearch® technology both revealed the presence of putative tumor cells that were positive for epithelial cell adhesion molecule (EpCAM) and cytokeratin (CK) expression." (PMID 25075284, 2014). "When Vγ9Vδ2 T cells from patient 2325 were cocultured with autologous EpCAM+ tumor cells in vitro, Vγ9Vδ2 T cells attached and killed tumor cells (movie clip S1)." (PMID 24515916, 2014). "Here, we performed flow cytometry and immunofluorescence staining and found that ALDH1Bright CSCs [identified as CD45−, EpCAM+ and propidium iodide (PI)−] composed roughly 6–10 % of tumor cells compared to normal human pancreas." (PMID 24652403, 2014). "Like the primary tumor cells, CTCs also express epithelial markers such as epithelial cell adhesion molecule (EpCAM) or certain cytokeratins (CKs)." (PMID 25521853, 2014). "The percentages of CD338high cells were determined in viable (SYTOX-), human (HLA-ABC+), epithelial (EpCAM+)-gated tumor-derived cells." (PMID 25216750, 2014). "This patient was also the only one to show high EPCAM-mRNA levels within the tumor both in WLT and LCM." (PMID 25141867, 2014). "Sal combined with 5-FU also inhibited the expression of CD133 and EPCAM respectively in subcutaneous tumor tissue of nude mice." (PMID 24816638, 2014). "In 131 different histological tumor types and subtypes, 33.6% of CTCs have low or positive expression of EpCAM." (PMID 25258614, 2014). "Although they are rare, the optical detection of such EpCAM+ tumor cells as done with the CellSearchTM system is in clinical use for a limited number of cancer entities." (PMID 25225495, 2014). "Catumaxomab anti-tumour activity has been demonstrated in vitro, notably in ascitic fluids, resulting in a decreased rate of EpCAM + cells and the release of pro-inflammatory cytokines (Interferon- γ, tumour necrosis factor-α, interleukin (IL)-2 and IL-6)." (PMID 24589307, 2014). "In this report we have demonstrated the involvement of EpCAM, integrin β4 and uPA in tumor cell migration and/or invasion--key steps in the metastatic cascade." (PMID 24885350, 2014). "Here, we demonstrate the targeted methylation and gene silencing of the EpCAM gene, which is a promising target in tumor therapy." (PMID 24489952, 2014). "CD44 and EpCAM, known to be present in a variety of tumor entities, were also expressed in tumor and lung metastases to a high degree." (PMID 24699516, 2014). "The discovery of the tumor-suppressive properties of EpCAM in some cancers has surprised many researchers, given its association with poor prognosis in many other cancers." (PMID 25265904, 2014). "Anti-EpCAM antibodies were used to identify circulating tumor cells in the blood of cancer patients, and to provide prognostic information that allows treatment of patients." (PMID 24489952, 2014). "Circulating tumor cells (CTCs) are commonly isolated from the blood by targeting the epithelial cell adhesion molecule (EpCAM) through positive selection." (PMID 24602188, 2014). "In the past decade, EpCAM (CD326) turned out to be a useful marker to detect circulating tumor cells (CTCs) or tumor stem cells." (PMID 25225495, 2014). "There are several tests commercially available which are based on the immunomagnetic enrichment of epithelial markers, especially EpCAM, therefore limiting the possibilities to detect mesenchymal tumor cells which have undergone EMT." (PMID 24895575, 2014).
tumor (continued). "While several groups have demonstrated the feasibility of accessing and analyzing circulating tumor, current approaches are largely limited by their reliance on EpCAM as a cell surface marker with which to differentiate tumor from WBCs in the blood or marrow." (PMID 25133137, 2014). "Catumaxomab, a nonhumanized chimeric antibody, is characterized by its unique ability to bind to three different types of cells: tumour cells expressing the epithelial cell adhesion molecule (EpCAM), T lymphocytes (CD3) and also accessory cells (Fcγ receptor)." (PMID 24589307, 2014). "Antisense knockdown of either EpCAM or claudin-7 reduces tumor growth and metastasis in mice, and knockdown of both is more effective." (PMID 24885350, 2014). "Tumor cell monitoring also revealed a reduction of EpCAM-positive malignant cells in ascites by up to 5 log." (PMID 25331657, 2014). "EPCAM can also contribute to tumorigenesis and metastasis by facilitating the immune escape of tumor cells." (PMID 24718422, 2014). "In conclusion, EpCAM a potential oncogene is a master regulator of several miRNAs and genes which are necessary for RB tumor progression." (PMID 25502397, 2014). "It is possible that a significant fraction of tumor cells may undergo extensive morphologic and behavioral changes to become migratory and invasive through epithelial to mesenchymal transition, resulting in CTCs with marked suppression or loss of EpCAM expression." (PMID 24551200, 2014). "Immunoflueorscence microscopy revealed that Vγ9Vδ2 T cells attached to and surrounded EpCAM+ tumor cells." (PMID 24515916, 2014). "Expression of the stem cell markers CD133 and EpCAM was confirmed in tumor and normal lung tissue by flow cytometry." (PMID 23959111, 2014). "In the other five patients, the number of EpCAM+ tumor cells in ascites fluid were significantly reduced after zoledronate and Vγ9Vδ2 T-cell treatment." (PMID 24515916, 2014). "Alterations in the expression of epithelial cell adhesion molecule (EpCAM) affect the sensitivity or resistance of tumor cells to anticancer treatment and the activity of intracellular signaling pathways." (PMID 25019346, 2014). "Unusually, miRNA which in our experimental data show up regulation on silencing EpCAM, are theoretically expected to be down regulated in tumors, since they are tumor suppressors." (PMID 25502397, 2014). "Our flow cytometric analysis showed that the DSF treatment caused a significant decrease in the number of tumor-initiating HCC cells expressing surface markers such as CD13, CD133, and EpCAM." (PMID 24454751, 2014). "EpCAM (also known as CD326) is well established as a tumor marker in many carcinomas, and is widely used to purify circulating tumor cells from blood." (PMID 24885350, 2014). "So far, catumaxomab, a trifunctional mAb, is used for the effective treatment of EpCAM-positive tumour cells in the peritoneal cavity." (PMID 26116117, 2014). "In agreement with previous reports our findings show numerous miRNAs in the 4 libraries (A33-Exos, EpCAM-Exos, sMVs, CL) associated with CRC (for a list of oncomiRs and tumour suppresssors found in our study)." (PMID 25330373, 2014). "Tumor cells loosing cell-cell contacts and invading host tissue are also loosing the strict basolateral distribution of EpCAM and show more cytoplasmic and membranous staining." (PMID 23758908, 2013). "EpCAM-targeted MBs efficiently (85%) and rapidly (within 15 minutes) bound to various epithelial tumor cells suspended in cell medium." (PMID 23516425, 2013). "The epithelial cell adhesion molecule (EpCAM; CD326) is a transmembrane glycoprotein, highly overexpressed on most carcinomas, and its downregulation inhibits the oncogenic potential of multiple tumor types." (PMID 24362576, 2013). "In fact, in HEK293 and FaDu tumor cell lines EpCAM has been reported to act directly on transcription of c-myc and cyclins." (PMID 23758908, 2013).
tumor (continued). "EpCAM's association with proliferation, adhesiveness, tissue stabilization, promotion of tumor growth, and metastasis suggests that EpCAM is a pleiotropic molecule that potentially offers therapeutic applications in cancer treatment." (PMID 23401782, 2013). "Diffuse type tumors presented a significantly higher EpCAM expression at the invasion front compared with the tumor centre (p=0.036)." (PMID 23830302, 2013). "In this report, we used the established PDX model at an early passage to initiate CSC propagation, resulting in a tumor spheroid culture enriched with CD133+/EpCAM+ cells." (PMID 23826249, 2013). "Expression of EPCAM correlated with age, tumor location, size of tumors, Lauren’s classification, depth of invasion, lymph node and distant metastases, regional lymph node stage, TNM stage and prognosis." (PMID 24422715, 2013). "The involvement of EpCAM in the regulation of proliferation was in the meantime studied in more detail and reported for several conditions including tumours." (PMID 24009667, 2013). "Tumor size was larger in the cHC-CCs than in HCCs (cHC-CCs vs. EpCAM(−)/K19(−) HCCs, P<0.001; cHC-CCs vs. EpCAM(+)/K19(+) HCCs, P = 0.033)." (PMID 24086533, 2013). "Recently, elevation of epithelial cell adhesion molecule (EpCAM) was reported to enhanced tumorsphere formation and tumor initiation." (PMID 23662112, 2013). "Within 28 days, xenotransplanted single cells generated tumours with a morphology and EpCAM expression pattern similar to the human carcinoma of origin." (PMID 23383219, 2013). "A possible explanation for this finding is that tumor infiltrating stromal cells diluted the percentage of CD133+/EpCAM+ cells." (PMID 23826249, 2013). "Because EpCAM is reported to be a diagnostic tumor-cell marker for HNSCC, the human EpCAM-positive cells were strictly gated to eliminate host-derived cells, and analyzed by flow cytometry." (PMID 23626764, 2013). "For expression analysis, all white blood cells comprising the tumour suspect cells from 1 mL of blood were stained with green fluorescence labelled anti-EpCAM." (PMID 23983815, 2013). "We observed a significant (p=0.001) correlation between high EpCAM expression and higher tumor cell proliferation." (PMID 23830302, 2013). "The most common strategy for isolating CTCs from blood is based on the use of immunomagnetic beads coated with anti-epithelial EpCAM, the most commonly used marker for detecting circulating tumor cells." (PMID 23516425, 2013). "Taken together, it appears that metformin impaired EpCAM+ tumor-initiating HCC cells and simultaneously promoted the differentiation towards non-TICs." (PMID 23922888, 2013). "Flow cytometric analysis showed that metformin treatment markedly reduced the number of tumor-initiating epithelial cell adhesion molecule (EpCAM)+ HCC cells." (PMID 23922888, 2013). "Peritoneal tumor cells of CRC origin frequently overexpress the epithelial cell-adhesion molecule (EpCAM)." (PMID 24380380, 2013). "Here we describe the capability of this aptamer, as well as a second aptamer against EpCAM, as an alternative to current EpCAM antibodies for chromogenic staining of formalin-fixed paraffin-embedded tumor tissues." (PMID 23460885, 2013). "Further study revealed EPCAM expression correlated with age, tumor location, tumor size, Lauren’s classification, depth of invasion, lymph node and distant metastases, regional lymph node stage, TNM stage and prognosis." (PMID 24422715, 2013). "The EpCAM antibody component of huKS-IL2 targets IL2 to EpCAM-positive tumors for the generation of cytotoxic T-cells and activation of the innate immune system, i.e. natural killer (NK) cells, in the tumor microenvironment." (PMID 23320927, 2013). "The analysis of a peripheral blood sample using the CellSearch system revealed the presence of circulating tumor cells (CTCs) that were positive for epithelial cell adhesion molecule (EpCAM) and cytokeratin (CK) expression." (PMID 24137345, 2013).